MAP3K3 (mitogen-activated protein kinase kinase kinase 3)
Diseases named in the same sentence as MAP3K3 in open-access papers (continued):
Sharing a sentence is not in itself a finding about the gene and the disease.
melanoma (2 papers, 2022 to 2024). A malignant, usually aggressive tumor composed of atypical, neoplastic melanocytes. "When we reviewed the expression levels of MAP3K3 and YAP, melanomas with MAP3K3 expression had higher expression levels of YAP than did melanomas without MAP3K3 expression (p = 0.0039)." (PMID 38622197, 2024). "Taken together, these results suggest that inhibition of MAP3K3 suppresses YAP function in melanoma cells." (PMID 38622197, 2024). "In this study, we demonstrated the potential role of MAP3K3 in BRAF inhibitor resistance in melanoma cells." (PMID 38622197, 2024). "Within the melanoma sequence data, we confirmed exon skipping in three genes–MAP3K3 (exon 3), FES (exon 11) and SLK (exon 13)." (PMID 35560144, 2022). "Similarly, elevated MAP3K3 expression supported the prosurvival activity of YAP in BRAF inhibitor-resistant melanoma cells." (PMID 38622197, 2024). "To test whether MAP3K3 knockdown can suppress the malignant behavior of vemurafenib-resistant melanoma cells, we examined the cell proliferation and migration ability abilities in vitro and the tumor formation capacity in xenografted immunocompromised mice." (PMID 38622197, 2024). "Another melanoma cell line, WM3248, also presented increased MAP3K3 and YAP levels after the acquisition of vemurafenib resistance." (PMID 38622197, 2024). "To evaluate the impact of MAP3K3 knockdown on the transcriptome of melanoma cells, we performed RNA-seq analysis with SKMEL28 cells harboring control or MAP3K3 shRNA." (PMID 38622197, 2024). "Therefore, we conclude that MAP3K3 contributes to YAP-dependent BRAF inhibitor resistance and other malignant behaviors in melanoma cells and is a promising target for anticancer drug development." (PMID 38622197, 2024). "Moreover, depletion of MAP3K3 decreased the tumorigenic potential and BRAF inhibitor resistance of melanoma cells." (PMID 38622197, 2024).
meningioma (2 papers, 2021 to 2022). A generally slow growing tumor attached to the dura mater. "A gene involved in the growth of NF2-negative meningiomas is TRAF7, an E3 ubiquitin ligase that interacts with MEKK3/MAP3K3 (mitogen-activated protein kinase kinase 3) and regulates apoptosis." (PMID 35565385, 2022).
Stroke (2 papers, 2025 to 2026). Sudden impairment of blood flow to a part of the brain due to occlusion or rupture of an artery to the brain. "The presence of a familial history of stroke and neurological problems suggests a possible interaction with the AIRE mutation, which may act as a genetic driver for the development of somatic MAP3K3 alterations, and raises questions about whether the variant is somatic or inherited." (PMID 41190326, 2025).
Venous malformation (2 papers, 2022 to 2025). A vascular malformation resulting from a developmental error of venous tissue composed of dysmorphic channels lined by flattened endothelium and exhibiting slow turnover. "MAP3K3 is an enzyme downstream of the angiopoietin 1 and tunica internal endothelial cell kinase pathway; alterations in the tunica internal endothelial cell kinase pathway are associated with venous malformations." (PMID 40948689, 2025). "Verrucous Venous Malformation (VVM) also called Formerly Verrucous Hemangioma, is a non-hereditary venous malformation, caused by activating somatic mutations (ASM) of the MAP3K3 (Mitogen-Activated Protein Kinase Kinase Kinase 3) gene (OMIM 602539), located on chromosome 17q23.3." (PMID 36293054, 2022).
arteriovenous malformations (1 paper, 2022). "Here, we identified a putative new tumor type characterized by the same dural location, a similar histopathological pattern and a frequent GJA4 p.Gly41Cys mutation (3/6 cases), distinct from genes implicated in CCM (CCM1/2/3, MAP3K3, PIK3CA) and arteriovenous malformations (KRAS) of the brain." (PMID 35642047, 2022).
colon cancer (1 paper, 2020). "FuSiOn identified ten kinases (BMP2K, DCLK3, LIMK2, MAP2K5/MEK5, MAP3K3/MEKK3, ROS1, SIK2, TAOK2, ULK1, and ULK2) whose depletion mimicked the phenotypic effect of p62 depletion in HCT116 colon cancer cells." (PMID 33101709, 2020).
congenital vascular malformation (1 paper, 2019). A congenital abnormality of the arteries and veins, lymph vessels or veins and lymph vessels. "Several somatic mutations in MAPK related genes, such as MAP kinase kinase 1 (MAP2K1 or MEK1), MAP kinase kinase kinase 3 (MAP3K3, or MEKK3), EPHB4 and TEK, have been found in congenital vascular malformations." (PMID 31067686, 2019).
hemorrhagic stroke (1 paper, 2025). A stroke caused by a bleed on the brain. "Above all, various reports highlighted an association between the detected somatic mutation in MAP3K3 and the occurrence of CCMs, which, in rare cases, can cause hemorrhagic stroke." (PMID 41190326, 2025).
intracerebral hemorrhage (1 paper, 2022). A cerebrovascular disorder characterized by bleeding into one or both cerebral hemispheres including the basal ganglia and the cerebral cortex. "Nine (23.7%) of the 38 patients with MAP3K3 somatic mutations presented with symptomatic events and corresponding overt intracerebral hemorrhage on the magnetic resonance imaging (MRI), whereas 11(91.7%) of the 12 patients with CCM gene somatic mutations exhibited overt intracerebral hemorrhage." (PMID 36090889, 2022).
ischemic cardiomyopathy (1 paper, 2026). Ischemic cardiomyopathy is a cardiomyopathy in which a weakness in the muscle of the heart due to inadequate oxygen delivery to the myocardium with coronary artery disease being the most common cause. "In human left ventricle tissue ischemic cardiomyopathy (ICM, GSE57338 35), MAP3K3 was also upregulated." (PMID 41356186, 2026).
malignant cutaneous melanoma (1 paper, 2024). "We surveyed the Cancer Genome Atlas cutaneous melanoma dataset using cBioPortal59 and found MAP3K3 alterations (mutation, amplification, or mRNA upregulation) in 12% of the tumor samples." (PMID 38622197, 2024). "To further demonstrate the potential role of MAP3K3 in stabilizing YAP in the context of cancer, we investigated the association between MAP3K3 and YAP expression in malignant cutaneous melanoma samples." (PMID 38622197, 2024). "We also report a correlation between MAP3K3 expression and the YAP protein abundance in cutaneous melanoma, and we demonstrate the efficient suppression of YAP-associated BRAF inhibitor resistance through MAP3K3 inhibition." (PMID 38622197, 2024). "Immunohistochemical staining for MAP3K3 and YAP was performed on specimens from 65 patients with cutaneous melanoma." (PMID 38622197, 2024).
non-alcoholic fatty liver disease (1 paper, 2021). "In non-alcoholic fatty liver disease (NAFLD), miR-122 targets HIF-1α, vimentin, and mitogen-activated protein kinase kinase kinase 3, which regulate steatosis." (PMID 34943825, 2021).
pancreatic disease (1 paper, 2021). "The present WGS, however, detected potentially pathogenic variants in the ATM, SUFU, DAB1, POLQ, MAP3K3, FGFBP3 and ACAD9 genes that co-segregated with pancreatic disease in single FPC families, and thus might predispose them to the disease." (PMID 34357098, 2021).
Proteus syndrome (1 paper, 2023). Proteus syndrome (PS) is a very rare and complex hamartomatous overgrowth disorder characterized by progressive overgrowth of the skeleton, skin, adipose, and central nervous systems. "The other disease-causing genes includes AKT1 for Proteus syndrome, MAP3K3 for verrucous venous malformation (VVM), GNA11 for DCMO, RASA1 and EPHB4 with germline or somatic mutations for capillary malformation-arteriovenous malformation (CM-AVM), and so on." (PMID 37658401, 2023). "In addition, we identified a novel AKT1 p.Q79K mutation in Proteus syndrome and MAP3K3 p.E387D mutation in verrucous venous malformation." (PMID 37658401, 2023).
small cell lung carcinoma (1 paper, 2023). Small cell lung cancer (SCLC) is a highly aggressive malignant neoplasm, accounting for 10-15% of lung cancer cases, characterized byrapid growth, and early metastasis. "Circ-LDLRAD3 was an oncogenic factor in non-small cell lung cancer through miR-491-5P / mitogen-activated protein kinase kinase kinase 3 (MAP3K3) and miR-137 / lysine (K)-specific demethylase 1A (SLC1A5) pathways." (PMID 37587156, 2023).
tumor (25 papers, 2013 to 2025). "Cancer is a common abnormality in PROS, and it is possible that metastatic forms of tumor cells with activating mutations in PIK3CA or MAP3K3 can invade tissue/vasculature, circulate in the blood, and reside in microvascular lesions, including CCMs." (PMID 37109059, 2023). "Cancer is a frequent occurrence in PROS, and it is plausible that tumor cells with activating mutations in PIK3CA or MAP3K3 may infiltrate tissues and blood vessels in metastatic forms, leading to the formation of microvascular lesions such as CCMs." (PMID 37109059, 2023). "Finally, MAGEH1, PODN, and MAP3K3 were identified as three mRNAsi-related tumor suppressor genes that were downregulated in tumor tissues and whose overexpression was associated with prolonged OS." (PMID 33912458, 2021). "The results from qRT-PCR also exhibited the increase of miR-129-3p expression and decrease of MAP3K3 expression in the neoplasms from sh-circSETDB1 group when compared with that from sh-NC group." (PMID 34789310, 2021). "Several studies have shown that MAP3K3 expression in tumor cells was relevant to cancer progression." (PMID 30652073, 2019). "Further analysis of the types of tumor-infiltrating immune cells and which genes are regulated by MAP3K3 in both tumor and immune cells in the tumor microenvironment in vivo are warranted." (PMID 26088427, 2015). "Further we observed that among the 43 MAP3K3 lymphocyte-positive (score 2 and 3) samples, 27 (62.8%) tumors also demonstrated positive staining (score 2 and 3) in tumor cells." (PMID 26088427, 2015). "To help determine how MAP3K3 affects tumor growth, we utilized flow cytometry analysis to examine the effect of MAP3K3 knockdown on the cell cycle." (PMID 26088427, 2015). "Hence, all evidences manifested circSETDB1 silencing inhibited tumor formation by regulating miR-129-3p and MAP3K3 expression in vivo." (PMID 34789310, 2021). "MiR‐194‐can directly target MAP3K3 to regulate tumor progression." (PMID 30652073, 2019). "MAP3K3 is involved in both the immune response and in tumor progression." (PMID 26088427, 2015). "This indicated that MAP3K3 knockdown suppressing tumor cell growth and invasion may through regulate AKT and GSK-3β pathways." (PMID 26088427, 2015). "Next, we evaluated the effects of MAP3K3 knockdown on both tumor cell migration and invasion." (PMID 26088427, 2015). "MAP3K3 overexpression correlates with a favorable patient outcome, and this may be due to the balance between an active immune response and tumor cell growth in the tumor microenvironment." (PMID 26088427, 2015). "TBC1D10C is a selective, constitutive suppressor of the CD8 T-cell antitumor response, and the Tbc1d10c–Map3k3–NF-κB signaling axis is a viable therapeutic target to promote CD8 T-cell antitumor immunity while circumventing CD4 T cell-associated cytotoxicity and NF-κB activation in tumor cells." (PMID 40761790, 2025). "Furthermore, multivariate Cox proportional hazards model analysis revealed that MAP3K3 mRNA remained a significant independent favorable prognostic factor after adjusting for age, gender, stage and tumor differentiation status (p = 0.03 and 0.003, respectively)." (PMID 26088427, 2015). "TBC1D10C mediates Map3k3-NF-κB signaling axis activation to inhibit CD8 T cell activation and anti-tumor function thus promoting tumor progression." (PMID 37006257, 2023). "In this investigation, it was observed that MAP3K1, MAP3K3, MAP3K5, MAP3K10, and MAP3K15 were upregulated in HCC tumor tissues, whereas MAP3K7, MAP3K8, MAP3K9, and MAP3K11 were downregulated in tumor tissues in GSE14520." (PMID 35311629, 2022). "The results of protein interaction analysis in Pathway Common also showed that MAPK upstream kinases (MAP3K3, MAP3K5), ERBB3 and ULK1, which are important for tumor cell growth and proliferation, can bind to NEDD4L." (PMID 34539897, 2021).
tumor (continued). "Conversely, down-regulation of MAP3K2 and MAP3K3 in CRC, as seen in GC, may lead to dysregulation of apoptosis, cell cycle control, and immune responses, contributing to tumor development and aggressiveness." (PMID 39901302, 2025). "Interestingly, depletion of MAP3K3, known to promote ovarian and NSCLC tumor growth, inhibited PDGFRA mutant GIST cell viability; however, no selective small molecule inhibitors are currently available to explore targeting MAP3K3 in GISTs." (PMID 33320833, 2021). "A large number of oncogenes as target genes of miR-505 in tumor cells, including TGF-α, HMGB1, FZD4, IGF1R, WNT7B, MAP3K3, NRCAM, and RUNX2, have been recognized as direct target genes of miR-505." (PMID 33520999, 2020). "Gene cluster and pathway analyses of primary tumor datasets indicated that genes positively-correlated with MAP3K3 are significantly involved in immune response rather than the cell cycle regulators observed using in vitro analyses." (PMID 26088427, 2015). "The favorable survival trend was clearer even for positive staining of MAP3K3 in both tumor and lymphocytes versus MAP3K3 negative staining in both samples (p = 0.01 for both positive vs. both negative)." (PMID 26088427, 2015). "This was significantly higher than the MAP3K3 tumor staining in the negative (score 0 and 1) lymphocyte group (14/45, 31.1%, p = 0.0006)." (PMID 26088427, 2015).
cancer (24 papers, 2014 to 2025). A tumor composed of atypical neoplastic, often pleomorphic cells that invade other tissues. "Biochemical researches indicate lots of MAPKs can be activated by MAP3K3, such as ERK1/2, c-Jun N-terminal kinases (JNKs) as well as p38, suggesting the importance of MAP3K3 in cancers." (PMID 34789310, 2021). "Using computational analysis, we found miR‐194 binds to the 3′ UTR of MAP3K3, while the knockdown of MAP3K3 suppresses cancer cell regression." (PMID 30652073, 2019). "In accordance, overexpressing MAP3K3 reversed the inhibition effects of miR‐194 in the tested carcinoma cells, consolidating the direct influence of miR‐194 on MAP3K3." (PMID 30652073, 2019). "In accordance, overexpression of MAP3K3 reversed the inhibitory effects of miR‐194 in carcinoma cells." (PMID 30652073, 2019). "The MAP3K3 protein is expressed in 34/61 (55.7) and 67.7% (63/93) of samples of esophageal dysplasia and cancer, respectively and its overexpression is related to reduced median disease-free survival." (PMID 26088427, 2015). "Moreover, it can regulate cancer cell proliferation and apoptosis by targeting different genes, including mitogen-activated protein kinase kinase kinase 3 (MAP3K3), SRY-box transcription factor 4 (SOX4), and methyltransferase like 3 (METTL3)." (PMID 39062744, 2024). "MAP3K3 has been identified as an oncogene in various cancers." (PMID 35560144, 2022). "Interestingly, EC is the human cancer that showed the higher percentage of cases wherein ERK5, MEK5, MAP3K2 and MAP3K3 are mutated." (PMID 36123565, 2022). "This suggests that focusing on MAP3K3 could be a good way to treat cancers that resist drugs." (PMID 38622197, 2024). "In addition, MEKK3/MAP3K3 overexpression is important in the development of cancer." (PMID 27119071, 2016). "In conclusion, our study reveals a previously unrecognized mechanism for the regulation of YAP stability, suggesting MAP3K3 inhibition as a promising strategy for overcoming resistance to CDK4/6 and BRAF inhibitors in cancer treatment." (PMID 38622197, 2024). "They found that another protein, MAP3K3, helps keep YAP stable, which then helps the body resist cancer drugs." (PMID 38622197, 2024). "Activating mutations in key factors of the PI3K/AKT/mTOR pathway, such as TIE2, PIK3CA, AKT, or MAP3K3, lead to the activation of PI3K signaling and uncontrolled cell proliferation in many human cancers." (PMID 37109059, 2023). "Activating mutations in key factors of the PI3K/AKT/mTOR pathway, such as PIK3CA, AKT, or MAP3K3, lead to the activation of PI3K signaling and uncontrolled cell proliferation in many human cancers." (PMID 37109059, 2023). "Our findings suggest that MAP3K3 is a promising target for alleviating drug resistance and that combination treatment with ponatinib with inhibitors of BRAF or CDK4/6 should be further tested as a YAP-targeting strategy in cancer treatment." (PMID 38622197, 2024). "However, further in vivo studies are needed to elucidate the importance of MAP3K3 and YAP in cancer progression and drug resistance." (PMID 38622197, 2024). "We were thereby able to show a positive correlation between BTN3A1, MAP3K3, and UBA7 expression and the majority of immune infiltrates (B cells, CD4 + T cells, CD8 + T cells, macrophages, and neutrophils) in most cancer types, and a negative correlation with myeloid dendritic cells." (PMID 39127727, 2024).
bacterial infections (1 paper, 2025). "External stimuli like bacterial infections or the inflammatory factor tumor necrosis factor-α activate mitogen-activated protein kinase MAP3K3 (also known as MEKK3), initiating downstream phosphorylation of mitogen-activated protein kinase 3/6 (MAP2K3/6)." (PMID 40242037, 2025).
MAP3K3 also shares sentences with these, for which no sentence is quoted: brain haemorrhage (2 papers); cardiac hypertrophy (2); cerebrovascular diseases (2); esophageal squamous cell carcinoma (2); hepatocellular carcinoma (2); infection (2); lymphoma (2); Obesity (2); osteoporosis (2); acute kidney injury (1); APECED syndrome (1); autoimmune disease (1); breast invasive carcinoma (1); choriocarcinoma (1); colorectal cancer (1); diabetes (1); dysplasia (1); epithelioid haemangioma (1); esophagus cancer (1); Ewing sarcoma (1); glioblastoma (1); glioma (1); Hyperkeratosis (1); hyperlipidemia (1); Hypertension (1); hypogonadism (1); Insulin resistance (1); kidney injury (1); leukemia (1); lung adenocarcinoma (1).
A further 8 diseases each share a sentence with MAP3K3 in 1 paper.